FERMT1 (FERM domain containing kindlin 1)
Diseases named in the same sentence as FERMT1 in open-access papers (continued):
Sharing a sentence is not in itself a finding about the gene and the disease.
glioma (5 papers, 2008 to 2025). A benign or malignant brain and spinal cord tumor that arises from glial cells (astrocytes, oligodendrocytes, ependymal cells). "Our results demonstrated that FERMT1 high expression is associated with good clinical outcomes, suggesting its potential as a prognostic biomarker for glioma." (PMID 38976072, 2024). "Moreover, FERMT1 knockdown significantly reduced sphere diameter, along with inhibiting the expression of transcription factors associated with stemness in glioma cells." (PMID 38976072, 2024). "Using data from TCGA-GBM, GSE4290, GSE50161 and GSE147352 for analysis of FERMT1 expression in glioma tissues." (PMID 38976072, 2024). "This study investigated the potential of FERMT1 as a prognostic biomarker and its role in regulating stemness through cell cycle in glioma." (PMID 38976072, 2024). "Transwell assays also demonstrated that FERMT1 deficiency markedly reduced the percentages of migrated and invasive cells compared to shNC cells, which characterized the role of FERMT1 in promoting cell metastasis in glioma." (PMID 38976072, 2024). "To validate the effect of FERMT1 in glioma, we employed shRNA-mediated knockdown to inhibit its expression in U-251 MG and T98G cells." (PMID 38976072, 2024). "In conclusion, we highlight the potential of FERMT1 as a prognostic biomarker for glioma and its involvement in regulating tumor progression, cellular metabolism and stemness in cancer cells." (PMID 38976072, 2024). "To investigate the involvement of FERMT1 in the maintenance of stem cell-like properties in human glioma cancer cells, we cultured U-251 MG and T98G cells with or without FERMT1 knockdown as 3D spheres." (PMID 38976072, 2024). "To gain insights into the functional role of FERMT1 in glioma cancer cells, we employed shRNA to silence its expression and analyze the consequential phenotypes." (PMID 38976072, 2024). "We examined the knockdown efficiency of three shRNAs to silence FERMT1 in 293T cells, and most effective one was selected for transfection in U-251 MG and T98G glioma cancer cells." (PMID 38976072, 2024). "Furthermore, to investigate the effect of FERMT1 knockdown on glioma CSCs, we examined the diameter of spheres formed by U-251 MG and T98G cells." (PMID 38976072, 2024). "Significant upregulation of FERMT1 in glioma tissues was observed." (PMID 38976072, 2024). "However, the involvement of FERMT1 in glioma and its effect on tumor progression and stemness remain largely uninvestigated." (PMID 38976072, 2024). "To explore the functional significance of FERMT1 in glioma progression and stemness, we hypothesized that silence of FERMT1 in glioma cancer cells would suppress tumor growth, invasion, and stemness properties." (PMID 38976072, 2024). "Our study aimed to explore the potential role of FERMT1 as a prognostic biomarker for glioma." (PMID 38976072, 2024). "Furthermore, the identification of FERMT1 as a potential therapeutic target may open up new avenues for the development of novel and effective treatment strategies against glioma." (PMID 38976072, 2024). "Other fc3 genes in the curated set, FERMT1, TMEM100, DYNLT3, EPHB1, IGFBP2, NNMT, and SH3GL2 all show direct evidence to a relationship with glioma biology and patient prognosis." (PMID 39941811, 2025). "To further explore the potential function of FERMT1 in glioma, we analyzed the KEGG and WP pathways related to difference in FERMT1 expression level." (PMID 38976072, 2024). "No published evidence was available as to the roles of the remaining eight underexpressed gene signatures (CHST9, CSDC2, ENHO, FERMT1, IGFN1, LINC00836, MGAT4C and SHANK2) regarding glioma pathogenesis or prognosis." (PMID 35456975, 2022).
glioma (continued). "FERMT1 knockdown significantly suppressed of MYC, OCT4 and NANOG expression in U-251 MG and T98G cells, which coordinately supported the regulatory role of FERMT1 in self-renewal and stem cell-like properties in glioma." (PMID 38976072, 2024). "At present, the molecular mechanism of FERMT1 affecting glioma through Wnt pathway has not been studied, and whether FERMT1 also affects downstream pathways by regulating β-catenin needs to be explored by further experiments." (PMID 38976072, 2024).
hepatocellular carcinoma (5 papers, 2020 to 2025). A malignant tumor that arises from hepatocytes. "Similarly, in hepatocellular carcinoma, PSMD14-mediated deubiquitination stabilizes CARM1, leading to the transcriptional activation of FERMT1 and subsequent promotion of proliferation and metastasis." (PMID 41488674, 2025).
colorectal cancer (4 papers, 2016 to 2024). A primary or metastatic malignant neoplasm that affects the colon or rectum. "While the role of FERMT1 in regulating tumor metastasis has been reported in colorectal cancer, oral cancer, and nasopharyngeal carcinoma, its involvement in NSCLC is unclear." (PMID 38200443, 2024).
nasopharyngeal carcinoma (4 papers, 2022 to 2024). A carcinoma arising from the nasopharyngeal epithelium. "Fermitin family member 1 (FERMT1) is significantly overexpressed in human cancers and associated with poor prognosis, but its contributions to tumorigenesis and nasopharyngeal carcinoma (NPC) progression remain unclear." (PMID 35144617, 2022).
colitis (3 papers, 2008 to 2023). Inflammation of the colon. "While the contribution of barrier dysfunction to mechanisms generating IBD remains incompletely understood, mutations in FERMT1 illustrate how breakdown of this barrier can result in colitis." (PMID 36248828, 2022).
epidermolysis bullosa (3 papers, 2023 to 2025). Epidermolysis bullosa (EB) is a group of genetic skin diseases that cause the skin to blister very easily. "It represents a subtype of inherited epidermolysis bullosa (EB) caused by mutations in the Fermitin family homologue 1 (FERMT1) gene, which encodes kindlin-1." (PMID 41195192, 2025).
oral squamous cell carcinoma (3 papers, 2021 to 2024). "It has been reported that FERMT1 and EMT play a regulatory role in cancer, for example, FERMT1 inhibits the migration, invasion and EMT of oral squamous cell carcinoma cells by inhibiting the PI3K/AKT signaling pathway, which becomes a new target for the anti-metastasis of cancer." (PMID 38976072, 2024).
psoriasis (3 papers, 2015 to 2025). An autoimmune condition characterized by red, well-delineated plaques with silvery scales that are usually on the extensor surfaces and scalp. "While EGFR has been verified target for miRNA-146a, another study identified FERMT1 as a psoriasis-related miRNA-146a target gene involved in keratinocyte proliferation." (PMID 41294623, 2025). "miR-146b facilitated miRNA-146a to inhibit the proliferation and psoriasis-related target gene expression (such as FERM domain containing kindlin 1 (FERMT1), NUMB endocytic adaptor protein (NUMB), etc.)in cultured human keratinocytes stimulated with IFN-γ or TNF-α." (PMID 35075118, 2022). "Of the most psoriasis-specific DEGPs, the majority were induced by IL-17A (e.g., FERMT1, GLUL, SULT2B1); in contrast, the most non-specific DEGPs were not disproportionately induced by IL-17A and several were repressed (e.g., AKR1B10, RNF213, ISG15)." (PMID 26251673, 2015).
asthma (1 paper, 2025). "Our top hits KCNJ10 and FERMT1 also showed association with asthma." (PMID 40410506, 2025).
COVID-19 (1 paper, 2022). A disease caused by infection with severe acute respiratory syndrome coronavirus 2. "Seven common DEGs (PPARGC1A, FUBP1, ITGB8, SYCP2, RSAD2, FGF1, and FERMT1) were identified from the GSE164805 dataset of patients with mild COVID-19, and the GSE50395 dataset from APS patients." (PMID 36241659, 2022).
oesophageal cancer (1 paper, 2020). "In oesophageal cancer, overexpression of FERMT1 by lenti-viral vector increased proliferation and radiation resistance in vitro." (PMID 32024004, 2020).
respiratory infections (1 paper, 2025). "The most common infections observed in the cohort were respiratory infections, especially in patients with LRBA deficiency, whereas patients with FERMT1 deficiency suffered gram-negative sepsis (Escherichia coli, Klebsiella pneumoniae)." (PMID 41142805, 2025).
ulcerative colitis (1 paper, 2008). An inflammatory bowel disease involving the mucosal surface of the large intestine and rectum. "Although a few KS patients have been reported to also develop ulcerative colitis (UC), a causal link to the FERMT1 gene mutation is unknown." (PMID 19057668, 2008).
tumor (33 papers, 2012 to 2026). "cBioPortal analysis of the TCGA pan-cancer cohort revealed that FERMT1 is infrequently mutationally altered (overall 1.2% mutation frequency) in most tumor types." (PMID 38982038, 2024). "The expression of FERMT1 was remarkably increased in patients with NSCLC and NSCLC cell lines, and FERMT1 was significantly associated with tumor grade and nodal metastasis." (PMID 33934696, 2021). "FERMT1 is involved in integrin signaling and the linkage of the actin cytoskeleton to the extracellular matrix, which plays an important role in enhancing tumor progression." (PMID 40016178, 2025). "PKP3 mRNA levels exhibited a significant increase in tumor tissues compared to normal tissues and displayed a positive correlation with FERMT1." (PMID 38200443, 2024). "Conversely, FERMT1 generally demonstrates hypomethylation across tumor types, except for prominent hypermethylation in BRCA." (PMID 38548811, 2024). "Through comprehensive analysis of multiple databases, we observed significant overexpression of FERMT1 in glioma cancer cells and upregulation of FERMT1 in tumor tissues, which is different with the FERMT1 expression in GSE108474 database." (PMID 38976072, 2024). "Since the immune cells in the tumor microenvironment are intimately connected with tumor progression and prognosis, the relationship between FERMT1 expression and the degree of immune infiltration was investigated in PAAD." (PMID 36981005, 2023). "CD8+ T and NK cells are considered to be the main anti-tumor immune cells, which partly explained the worse prognosis of high FERMT1 expression in PAAD patients." (PMID 36981005, 2023). "FERMT1 is considered to be involved in tumor proliferation, apoptosis, metastasis, and tumor angiogenesis." (PMID 36981005, 2023). "Cell migration in vitro and tumor growth in vivo are suppressed by the ectopic expression of FERMT1 in NSCLC cells." (PMID 36981005, 2023). "Prior studies have revealed that FERMT1 is overexpressed and acts as a tumor promoter in various cancer types, including breast, colon, pancreatic, and hepatocellular cancer." (PMID 33934696, 2021). "Our study demonstrated that FERMT1 activates the NF-κB signaling pathway by promoting the degradation of IκBα, thus resulting in GC tumor progression." (PMID 32723205, 2020). "Moreover, accumulating evidence suggests a role for FERMT1 in tumor proliferation, metastasis, apoptosis, and angiogenesis." (PMID 39309641, 2024). "Furthermore, expression of FERMT1 has been correlated with immune infiltration in pancreatic adenocarcinoma patients, supporting a role in influencing adaptive anti-tumour immunity." (PMID 39641590, 2024). "Silencing FERMT1 expression in NPC could reduce tumor proliferation, migration and invasion by reversing EMT and the cell cycle in vitro and in vivo." (PMID 35144617, 2022). "It seems likely that FERMT1 is a tumor driver in cutaneous epithelial cells." (PMID 35144617, 2022). "Mechanistically, several interesting linkages have indicated that FERMT1 may be involved in tumor occurrence and development by regulating the transforming growth factor-beta (TGFβ) signaling." (PMID 33934696, 2021). "Furthermore, growing evidence has confirmed that FERMT1 might play a role in tumor proliferation, metastasis, apoptosis, and tumor angiogenesis." (PMID 35144617, 2022). "In humans, the expression of SLC12A2, FERMT1, NCL, NOP56, and NOXA1 was significantly upregulated in human tumor cells compared to that in normal controls." (PMID 38886341, 2024). "ITGA8 and ADAMTS8 were downregulated in tumor tissues, whereas FERMT1, CTSV, CPS1, ENTPD2, SERPINB5, and LYPD3 were upregulated in tumor tissues." (PMID 35557945, 2022). "We knocked down FERMT1 expression by lentiviral shRNA and subsequently found that FERMT1 expression depletion suppressed NPC cell proliferation and tumor growth in vitro and in vivo." (PMID 35144617, 2022).
tumor (continued). "The expression of two proteins (FERMT1, and PLEK2) in LUAD cancer were higher in tumor tissues (66.6%) than in normal tissues." (PMID 36428765, 2022). "It was reported that FERMT1 was overexpressed in NSCLC and inhibited tumor epithelial-mesenchymal transition, growth and invasion." (PMID 33934696, 2021). "After overexpression of FERMT1, mice implanted with FERMT1 overexpressing MKN45 cells, compared with vector control cells, showed greater tumor volume and weight." (PMID 32723205, 2020). "To test this, we performed an identical CRISPR screen in vitro, where ITGB1, FERMT1, and CD151 proved less important for tumor growth than in vivo." (PMID 32579974, 2020). "FERMT1 expression did not correlate with pathological differentiation status, tumor depth, tumor diameter or tumor invasion status." (PMID 38982038, 2024). "In addition, we assessed the expression of molecules such as ANKRD22, GINS3, POLE2, PLEK2, FERMT1 and METTL14 in subcutaneous tumours and lung metastatic tissues." (PMID 39021049, 2024). "FERMT1 forms molecular complexes with focal adhesion kinase (FAK), β1-integrins, α-actinin and migfilin to modulate cell shape and migration, while TAE226, a FAK inhibitor, has inhibitory effects on the growth of a variety of tumor cells." (PMID 36981005, 2023). "The expression levels of FERMT1 and FERMT2 were remarkably distinct in different tumor stages of LUAD and LUSC, while there was no significance between FERMT3 and different tumor stages." (PMID 33934696, 2021).
cancer (25 papers, 2008 to 2024). A tumor composed of atypical neoplastic, often pleomorphic cells that invade other tissues. "Dysregulated expression of the FERMT1 gene in diverse malignant tumors is intricately linked to the initiation and progression of tumors." (PMID 38200443, 2024). "The FERMT1 gene mutates and causes symptoms such as blistering and epidermal atrophy, as well as an increased risk of cancer and poor wound healing." (PMID 38765347, 2024). "As with the other genes mentioned, FERMT1 has reported associations with cancer, likely through B-catenin regulation." (PMID 34648530, 2021). "Interestingly, hypermethylation of FERMT1 and FERMT2is a survival risk marker in various cancers, including LGG, ACC, KIRC, and SARC." (PMID 38548811, 2024). "FERMT1 deficiency may correlate with heightened cancer risk, underlining the necessity for ongoing patient monitoring to facilitate the early identification and treatment of potential malignancies." (PMID 39309641, 2024). "In our sample cohort, we found that both FERMT1 were overexpressed in 11 cancer types including CESC, LUAD, STAD, ESCA etc. but underexpressed in 6 cancer types." (PMID 38548811, 2024). "FERMT1 promotes cell migration and infiltration by binding to integrins in the extracellular matrix, thereby promoting the metastasis and dissemination of cancer cells." (PMID 39610830, 2024). "Its involvement in diverse cellular functions underscores the significance of FERMT1 in cancer development and progression." (PMID 38976072, 2024). "Compared with normal tissues, the mRNA expression level of FERMT1 was considerably increased in 12 types of cancer including PAAD." (PMID 36981005, 2023). "Specifically, we observed that FERMT1 is recurrently amplified across many subtypes of cancer, suggesting a broadly pro-tumorigenic role." (PMID 32579974, 2020). "In these cancers, TGFβ signaling appears to be a major factor in the carcinogenic effects of FERMT1." (PMID 32723205, 2020). "FERMT1 assumes a pivotal role in mediating integrin-dependent cell adhesion and signaling, which encompasses a wide array of physiological and pathological processes including cancer progression." (PMID 38976072, 2024). "Additional studies suggest a role for FERMT1 in regulating EMT across multiple cancers including." (PMID 35666359, 2022). "Fermitin family member 1 (FERMT1) plays an -oncogene role in many cancers; however, the role of FERMT1 in oral squamous cell cancer (OSCC) remains unclear." (PMID 34814915, 2021). "In addition, FERMT1 has been shown to play a cancer-promoting role by regulating the Wnt pathway." (PMID 38976072, 2024). "Among these cancers, TGF-β signaling appeared to be an important factor in the carcinogenic effect of FERMT1." (PMID 35144617, 2022). "FERMT1 expression increased with increasing stage of cancer progression in BLCA, COAD, LUSC, and STAD." (PMID 38548811, 2024). "Overexpression of FERMT1 was observed in primary cancer with distant metastasis compared with primary cancer without distant metastasis." (PMID 32723205, 2020). "FERMT1, MET, and MMP3 overexpressed in PC tissues, while the expressions of CARD9 were not outstanding in both normal and cancer tissues in PC." (PMID 37727377, 2023).
genodermatosis (3 papers, 2008 to 2024). "In spite of the knowledge underlying cause of this disease involving mutations of FERMT1 (fermitin family member 1), and efforts to characterize genotype-phenotype correlations, the clinical variability of this genodermatosis is still poorly understood." (PMID 25528446, 2014).
adenocarcinoma (2 papers, 2012 to 2015). A common cancer characterized by the presence of malignant glandular cells. "Of the canonical changes noted, promoter (PR) DM loci with reciprocal changes in expression in adenocarcinomas included HBEGF, AGER, PTPRM, DPT, CST1, MELK; DM GB loci with concordant changes in expression included FOXM1, FERMT1, SLC7A5, and FAP genes." (PMID 26683690, 2015).
cardiovascular disease (1 paper, 2022). "On the contrary, FERMT1 and CCNI2 have no direct link with any form of cardiovascular disease so far although they may have some unknown functions in AF." (PMID 36078037, 2022).
infection (1 paper, 2019). The state of being infected such as from the introduction of a foreign agent such as serum, vaccine, antigenic substance or organism. "Conversely, the top 12 downregulated genes, including fermitin family member 1 (FERMT1), signal peptide peptidase like 3 (SPPL3), and tetratricopeptide repeat domain 19 (TTC19), negatively correlated with VA1 infection." (PMID 31671153, 2019).
skin disorder (1 paper, 2024). Any deviation from the normal structure or function of the skin or subcutaneous tissue that is manifested by a characteristic set of symptoms and signs. "In a previous study, homozygous sequence variants of FERMT1 were found to be correlated with skin disorders in various human families through exome sequencing." (PMID 39728991, 2024).